APOE (apolipoprotein E)
Diseases named in the same sentence as APOE in open-access papers (continued):
Sharing a sentence is not in itself a finding about the gene and the disease.
atherosclerosis (continued). "The serum levels of atherosclerosis-related inflammatory factors in ApoE−/− mice were measured by mouse atherosclerosis antibody array I." (PMID 25889019, 2015). "The difference in atherosclerosis-susceptibility between FVB/N and B6 mice has been studied in some depth in the setting of apoE or LDL receptor deficiency." (PMID 25875831, 2015). "The network consists of 114 protein abundances and 42 RNA abundances as well as 43 biological processes involved in atherosclerosis plaque destabilization in ApoE−/−mice." (PMID 26200752, 2015). "CCL5 levels were assessed in plasma from arsenic-exposed apoE-/- mice after 8 and 13 weeks, time points where significant arsenic-enhanced atherosclerosis is observed." (PMID 26332580, 2015). "The ApoE−/− mouse develops spontaneous hypercholesterolemia and atherosclerosis with the first signs of disease occurring at 6 to 8 weeks with features accelerated by high fat feeding." (PMID 26196300, 2015). "In cardiovascular disease alone hypertension has been related to atherosclerosis development however, blood pressure in the apoE-/- mouse is unaffected by CKD and as such unlikely to contribute to vascular dysfunction." (PMID 25799529, 2015). "Sesquiterpene lactones have been shown in apoE-/- mice and guinea pigs to have anti-atherosclerosis efficacy via their anti-inflammatory activities." (PMID 26064179, 2015). "It has been shown that an endothelial-specific increase in Nox2-derived superoxide production is sufficient to alter macrophage recruitment and endothelial cell activation, key factors in the initiation of atherosclerosis in ApoE−/− mice." (PMID 25866599, 2015). "The present study attempted to further clarify the role of NADPH oxidases subunit p47phox in the setting of atherosclerosis using apoE(-/-) murine model." (PMID 25628043, 2015). "The ApoE null mouse is a well-established model for studying atherosclerosis (macrovascular disease) as well as hyperlipidemic renal injury (microvascular disease)." (PMID 25803585, 2015). "This is the first investigation to show that exercise is effective at reducing atherosclerosis burden in apoE-/- mice with kidney disease." (PMID 25799529, 2015). "Recently, high fat diet (60% fat) fed ApoE-/- mice has been demonstrated to be an animal model of obesity induced accelerated atherosclerosis." (PMID 25803585, 2015). "We investigated its use as a preventive agent against inflammatory and vascular diseases in a murine model of atherosclerosis using apolipoprotein E-knockout (ApoE−/−) mice fed on a high-fat diet (HFD)." (PMID 26174316, 2015). "A previous study found that activated platelets exacerbated atherosclerosis through the repeated injection of activated platelets into ApoE-/- mice." (PMID 26053836, 2015). "This study was designed to determine the effects of miR-590 on lipoprotein lipase (LPL) expression and development of atherosclerosis in apolipoprotein E knockout (apoE−/−) mice and explore the potential mechanisms." (PMID 26397958, 2015). "Apolipoprotein E (ApoE) is known to play a protective role in preventing artery wall thickening in atherosclerosis and ApoE-/- mice show mtDNA damage before significant atherosclerosis." (PMID 27508052, 2015). "The importance of HMGB1 in the development of atherosclerosis has been demonstrated in apoE-/- transgenic mice." (PMID 25884983, 2015).
atherosclerosis (continued). "To determine the physiologic AR-dependent actions of androgens on the development of atherosclerosis in females, we generated female ARKO and control mice on an atherosclerosis-prone apolipoprotein E (apoE)–deficient background." (PMID 25550469, 2015). "Mice deficient in the receptor for low-density lipoprotein (LDL) or in apolipoprotein E develop hypercholesterolemia and subsequent atherosclerosis when fed an atherogenic diet." (PMID 25770018, 2015). "Similar with our results, the other studies have demonstrated that perivascular adipose tissues play a role in the pathogenesis of atherosclerosis in ApoE-/- mice." (PMID 26020520, 2015). "The aim of the present study was to determine the influence of exercise on the development of atherosclerosis, vascular dysfunction and systemic inflammation in apoE-/- mice with 5/6 nephrectomies." (PMID 25799529, 2015). "Here, in the perivascular collar placement around carotid artery combined with feeding a high-fat diet ApoE−/− mouse model of accelerated atherosclerosis, PVAT-derived APN effectively suppressed collar-induced carotid atherosclerosis." (PMID 26020520, 2015). "apoE−/− mice fed by high-fat diet had the lesion characteristics of serious dyslipidemia and atherosclerosis, which were relatively good animal model for the research on atherosclerosis." (PMID 26074989, 2015). "Impairment of endothelial dependent relaxation, elevated resting pro-inflammatory cytokine concentrations and the progression of atherosclerosis in the apoE-/- mouse are highly dependent on dietary fat content." (PMID 25799529, 2015). "To this end, we performed a RNA-seq-based gene expression analysis in aortic atherosclerotic lesions of one 1.6 years old male APOE-null mouse, a model of hyperlipidemia-induced atherosclerosis and one congenic, sex- and age-matched WT sibling." (PMID 25881171, 2015). "Our data showed that TLR9 inhibition in ApoE−/− mice displayed a modest decrease (34.9% in aortic root and 23.0% in the whole aorta tree) in the extent of atherosclerosis." (PMID 26257462, 2015). "To determine the effect of CIT on atherosclerosis, we fed 5-week-old apolipoprotein E knockout (apoE-/-) mice with high-fat diets, and treated them with CIT for 15 weeks." (PMID 25933220, 2015). "Obese insulin resistant ob/ob mice displayed beneficial outcomes while atherosclerosis prone APOE-/- mice developed dyslipidemia and atherosclerotic plaques." (PMID 25695432, 2015). "Similar to the transgenic mice on C57Bl/6N background, the Tie2-Scarb1 × apoE-KO mice had less atherosclerosis on a normal chow diet than apoE-KO mice, again indicating that endothelial expression of SR-BI is atheroprotective." (PMID 26504816, 2015). "The results from the study showed that CCC can dramatically ameliorate atherosclerosis in the ApoE−/− mice fed with high-fat diet." (PMID 26539229, 2015). "Ly6Chigh monocytes, the murine correlate of human classical monocytes, drive atherosclerosis in transgenic animal models based on the genetic deletion of apolipoprotein E or the LDL receptor." (PMID 25852821, 2015). "In our apoE-/- mouse model of atherosclerosis, arsenic increased vascular expression of VCAM-1 and monocyte expression of active CD29." (PMID 26332580, 2015). "Overexpression of SR-BI in endothelium was also able to decrease atherosclerosis when crossed with apoE-KO mice." (PMID 26504816, 2015). "A previous study combining D-tagatose with another naturally occurring antioxidant, polydatin, found the combination to be effective in lowering total cholesterol and preventing the formation of atherosclerosis in ApoE-/- mice." (PMID 27683620, 2015). "In this study, we have investigated the role of TLR4/NF-κB pathway in CUMS-induced atherosclerosis in apoE-/- mice." (PMID 25860573, 2015).
atherosclerosis (continued). "Serum pro-inflammatory cytokines reduction in response to EXE has also been reported in ApoE-/- mice with advanced atherosclerosis." (PMID 26600018, 2015). "Dietary L-carnitine, a TMA abundant in red meat, is metabolized by intestinal microbiota to TMAO and accelerates atherosclerosis in ApoE-null mice through changes in microbial composition and increased colon production of TMA and TMAO." (PMID 26175728, 2015). "To test the effect of water restriction on development of atherosclerosis, we used apolipoprotein E knockout (ApoE-/-) mice." (PMID 26042828, 2015). "We recently reported that exercise prevents the development of Angiotensin (Ang) II-induced advanced atherosclerosis and plaque vulnerability, using the 2-kiney, 1-clip ApoE-/- mouse model." (PMID 26600018, 2015). "In vivo, the knockdown of P2X7R in apoE−/− mice significantly delayed the development of atherosclerosis with lower plasma levels of IL-1β." (PMID 25761252, 2015). "Other researchers have also reported that GLP-1 prevented the development of atherosclerosis in apolipoprotein E knockout mice." (PMID 26379274, 2015). "Even though further studies should address the role of VDR in lipid metabolism, our current results suggest that the more severe atherosclerosis in apoE-/-VDR-/- mice occurred despite improved serum lipid profiles." (PMID 26322890, 2015). "The effects of Iso on atherosclerosis in vivo were also evaluated in apolipoprotein E knockout (ApoE-/-) mice fed a high fat diet." (PMID 25799286, 2015). "The Western diet promoted obesity, increased total serum cholesterol, and markedly stimulated the development of atherosclerosis in the ApoE−/− mice compared to mice on Standard chow." (PMID 27683620, 2015). "Apolipoprotein E3 (apoE3) is thought to protect against atherosclerosis by enhancing reverse cholesterol transport." (PMID 26068461, 2015). "To study the effects of VDR deletion on atherosclerotic plaque development in vivo, we combined a genetic model of VDR deletion with a mouse model of experimental atherosclerosis, the apolipoprotein E knockout (apoE-/-) mouse." (PMID 26322890, 2015). "The disruption of endothelial integrity is an early key event during the pathogensis of atherosclerosis, and endothelial dysfunction was observed in apoE−/− mice fed a high-cholesterol diet for 7 weeks." (PMID 25874925, 2015). "Effects of the extract on expression of atherosclerosis-related adhesion molecules and anti-inflammatory signaling in human smooth muscle cells (HASMCs), as well as in ApoE−/− mouse aortas, were assessed." (PMID 26174316, 2015). "ApoE-/- mice have elevated plasma cholesterol levels and spontaneously develop atherosclerosis, a multistep process driven by inflammation." (PMID 25799423, 2015). "The onset of CKD in apoE-/- mice accelerates atherosclerosis and increases thickening of the aortic valves, in combination with elevating inflammatory cytokines." (PMID 25799529, 2015). "The atherogenic role of these signaling molecules is supported by observations in ApoE-null mice deficient for TLR2, TLR4, or MyD88 that have attenuated atherosclerosis." (PMID 26175728, 2015). "This study examined the effect of the addition of BSN723, D-tagatose, or a combination of the two, on weight gain, blood lipids, and the development of atherosclerosis, in ApoE-/- mice consuming a Western diet (high fat, high cholesterol, high sucrose diet)." (PMID 27683620, 2015). "Single deletion of mouse SR-BI accelerates atherosclerosis, whereas combined deletion of SR-BI and ApoE mimics several features of human coronary disease, including occlusive atherosclerosis, myocardial infarction, and premature death." (PMID 26059978, 2015).
atherosclerosis (continued). "This study is designed to study the mechanism of CCC on atherosclerosis in the ApoE-knockout (ApoE−/−) mice fed with a high-fat diet." (PMID 26539229, 2015). "In this study human MSCs were transferred to ApoE KO mice, which increased eNOS in the aorta and thereby increased vasodilation in ApoE KO mice, but only resulted in a mild reduction of atherosclerosis." (PMID 26490642, 2015). "The impact of PEP-1-MsrA injection on the development of atherosclerosis in apoE−/− mice was assessed." (PMID 26410585, 2015). "In this study, we collected the peritoneal macrophages from ApoE−/− mice, which have become the most widely used rodent model for the study of atherosclerosis." (PMID 26557864, 2015). "We were particularly interested in apoE-/- mice, because this hyperlipidemic strain was used in our in vivo model of arsenic enhanced atherosclerosis." (PMID 26332580, 2015). "Ambient PM10 exposure had also been reported to induce considerable oxidative stress and systemic inflammation in ApoE knockout mice and contributed to the progression of atherosclerosis." (PMID 26445316, 2015). "Development of atherosclerosis in the aorta, as assessed by en face Oil Red O staining, was reduced by almost 60% in ApoE/mdx mice as compared to ApoE mice." (PMID 26345322, 2015). "It is interesting that the transfer of miR-143/145 from ECs to VSMCs through microvesicles reduces atherosclerosis and promotes a contractile VSMCs phenotype in the aorta of ApoE−/− mice." (PMID 25710020, 2015). "The ApoE−/− and ApoE−/−:Pak1−/− mice were then fed with Western diet (WD) for 16 weeks, starting from 8 weeks of age, and atherosclerosis was assessed by evaluating the lesion size and its composition in the aorta and aortic root." (PMID 26104863, 2015). "Herein, we show that MED can inhibit foam cell formation and cytokine production induced by ox-LDL in macrophages and protect ApoE−/− mice from atherosclerosis by blocking the NF-κB signaling." (PMID 26045945, 2015). "AMP-dNM treatment restores insulin sensitivity in ob/ob mice and also inhibits atherosclerosis in APOE*3 Leiden as well as low-density lipoprotein receptor−/− mice." (PMID 26338710, 2015). "In murine models of atherosclerosis, IL-18BP reduces fatty streak development, and slows progression of advanced atherosclerotic plaques in the thoracic aorta of apoE knockout mice." (PMID 25699211, 2015). "ApoE−/− mice develop atherosclerosis spontaneously as they age, and plaque development is enhanced and accelerated by a high fat diet." (PMID 25993289, 2015). "The apoE knockout mouse model used here is a well-established genetic model of atherosclerosis, but it is a more severe mouse model than others that exist." (PMID 25972522, 2015). "For this reason we used CF1 mice fed a high fat diet, a model of early stage of CVD, and ApoE knockout mice, a model of atherosclerosis, to study the impact of apple peel consumption." (PMID 26075004, 2015). "Mice are normally resistant to the development of atherosclerosis, however inactivation of the apoE gene in mice results in elevated cholesterol and triglycerides in these mice." (PMID 27683620, 2015). "The aim of this study was to investigate the effects of AsIV on blood lipids, CD40-CD40L signal system, and SDF-1/CXCR4 biological axis in high-fat diet apoE−/− mice and reveal the molecular mechanisms of AsIV against atherosclerosis." (PMID 26074989, 2015). "In the advanced atherosclerosis model obtained in ApoE−/− mice fed with FD + HAP, we observed a significant decrease of the fat content at the atheroma plaque, expressed as a lipid infiltration area." (PMID 26075004, 2015). "ApoE-/- mice have impaired clearance of plasma lipoproteins and develop atherosclerosis in a short time, making them a convenient model to assess impact of different factors." (PMID 26042828, 2015).
atherosclerosis (continued). "In this study we examined late effects of low-dose irradiation with specific emphasis on heart microvascular damage, using an atherosclerosis-prone ApoE-/- mouse model." (PMID 25799423, 2015). "That the absence of PPARα also prevents L-NAME-induced atherosclerosis on the genetic background of ApoE-KO, reemphasizes the role of this gene in the development of atherosclerosis driven by several different triggers." (PMID 24587793, 2014). "Deletion of Ccr6 decreased atherosclerosis burden in the ApoE−/− mouse, which was accompanied by lower macrophage content in plaques, suggesting that CCR6 is proatherogenic." (PMID 24741577, 2014). "CF-1 mice fed a fat diet were used to obtain early stages of atheromatous process, denominated early stage of atherosclerosis, and ApoE−/− mice fed a fat diet were used to observe advanced stages of atherosclerosis." (PMID 25328689, 2014). "Experimentally, atherosclerosis can be induced by the inactivation of the apolipoprotein-E (apoE) gene by homologous recombination." (PMID 25422135, 2014). "Exposure to low levels of corticosterone for long terms significantly exacerbates atherosclerosis in ApoE knockout mice." (PMID 25189624, 2014). "For example, in apoE-deficient mice, natural protective IgM antibodes against oxidized phospholipids of Streptococcus pneumoniae were detected and measurement of these atherosclerosis-unrelated antibodies could aberrantly increase the total titer of oxLDL antibodies." (PMID 25050779, 2014). "Alirocumab dose-dependently decreases plasma lipids and, as a result, atherosclerosis development, and it enhances the beneficial effects of atorvastatin in APOE*3Leiden.CETP mice." (PMID 25139399, 2014). "The aim of this study was to investigate the effects of occlusal disharmony on the initiation of atherosclerosis in apoE knockout rats as an established atherosclerosis model." (PMID 25189624, 2014). "The effect of NR1 on atherosclerosis lesion formation in ApoE−/− mice was first examined by treated the mice with NR1 at the dose of 25 mg/Kg bw for 8 weeks." (PMID 24933211, 2014). "In this study, we produced CSE transgenic ApoE-KO (Tg/KO) mice to examine the anti-atherogenic effect of H2S as compared to ApoE-KO (KO) mice, a mice model for atherosclerosis." (PMID 25397776, 2014). "ApoE−/− mice infected with this strain exhibited diminished vascular inflammation, macrophage accumulation, and atherosclerosis progression." (PMID 25010102, 2014). "The aim of this study was to investigate the effects of two dosages of alirocumab alone and in combination with atorvastatin on plasma lipids, atherosclerosis development, and lesion composition in APOE*3Leiden.CETP mice." (PMID 25139399, 2014). "In this study, the authors demonstrated that in a hypercholesterolemic apoE transgenic mouse model, local delivery of 6-MP reduced atherosclerosis, mainly due to reduced activation of monocytes." (PMID 25029363, 2014). "Evidence for a role of platelet reactivity in the progression of atherosclerosis was previously shown by infusion of activated platelets into ApoE knockout mice." (PMID 25122139, 2014). "The aim of the present study was to evaluate the effect of metoprolol on development of atherosclerosis in ApoE−/− mice and investigate its effect on the release of proinflammatory cytokines." (PMID 25105129, 2014). "A recent report indicated ethanolic extract of propolis inhibited atherosclerosis in ApoE-knockout mice." (PMID 24864152, 2014). "Inhibition of endothelial nitric oxide synthase (eNOS) accelerates atherosclerosis in ApoE-null mice by impairing the balance between angiotensin II (AII) and NO." (PMID 24587793, 2014). "Mir-144-3p targeting ABCA1, the doorkeeper of RCT, resulted in impaired cholesterol efflux and boosted inflammatory response, which effectively accelerated the occurrence and progression of atherosclerosis in apoE−/− mice fed HFD." (PMID 24733347, 2014).